EGF (epidermal growth factor)
Diseases named in the same sentence as EGF in open-access papers (continued):
Sharing a sentence is not in itself a finding about the gene and the disease.
cancer (continued). "Recent studies documented that IGFBP-3, one of EGFR downstream targets, plays an important role in modulation of radiosensitivity of different human cancers, and EGF could down-regulate IGFBP-3 expression in esophageal squamous carcinoma cells." (PMID 23232108, 2012). "Finding an effective way to suppress tumor migration by limiting the EGF-induced cell de-adhesion might contribute to the development of a potentially more effective cancer treatment." (PMID 25586035, 2012). "Although targeting FGF2 signalling as a cancer therapy has been lagging behind that of other receptor tyrosine kinases, including epidermal growth factor (EGF) signalling, clinical reagents that specifically target the FGFs or FGF receptors are being developed and included in clinical trials." (PMID 22732006, 2012). "On the other hand, EGF stimulation of its receptor, which also belongs to a family of receptor tyrosine kinases, has been shown to induce two transient increases F-actin of motile carcinoma cells." (PMID 22279563, 2012). "Interestingly, whereas EGF-induced carcinoma cell migration on vitronectin is sensitive to Src inhibition as expected, cell migration driven by the MUC1 cytoplasmic domain does not require Src kinase activity." (PMID 22586492, 2012). "Moreover, cell migration and metastasis mediated by integrin αvβ5 requires the EGF-dependent activation of Src, which in turn is sufficient for carcinoma cell migration and metastasis." (PMID 22586492, 2012). "Indeed, treatment of EGFR-positive cancer cells with CL4 strongly inhibits both the EGF-induced tyrosine phosphorylation of EGFR and ErbB2 and the Hrg-dependent tyrosine phosphorylation of EGFR and ErbB3." (PMID 21915281, 2011). "PI3K activity supports EGF/serum induced survival of cancer cells, through phosphorylation-mediated inactivation of BAD although other kinases could also control Ser75 phosphorylation." (PMID 21880146, 2011). "The clinical evaluation of the EGF cancer vaccine started 15 years ago." (PMID 22024351, 2011). "Moreover numerous studies have demonstrated that stimulation of human cancer cells with EGF results in an increase in the intracellular concentration of ROS." (PMID 22194952, 2011). "In addition, some of the top signaling pathways (JAK/STAT, TGF-β, epidermal growth factor and Wnt/β-catenin signaling) overlapped the signaling pathways important for cancer stem-like cells, identified between the MCF-7 side population (SP) and non-SP cells." (PMID 20696077, 2010). "As IGF-1 and EGF are both known to stimulate survivin in cancer cells, we next tested whether these growth factors can also induce survivin in pancreatic β-cells." (PMID 20807437, 2010). "Cancer is a complex disease, EGF +61 G/A might play different roles in different kinds of cancers; Ethnic difference may also contribute to different disease susceptibility; Sample size must be large enough to be convincing." (PMID 20487573, 2010). "Epidermal growth factor (EGF) is critical in cancer process." (PMID 20487573, 2010). "The EGF-EGFR signaling pathway performed an important role in regulating cell proliferation, migration, adhesion, and inflammatory processes, the correlation between this particular polymorphism and cancer have practical value." (PMID 20487573, 2010). "We believe that this finding supports the use of EGF in cancer patients." (PMID 19456848, 2009). "A newer approach for treating EGF-overexpressing cancers involves EGF receptor inhibitors (EGFRIs)." (PMID 19816581, 2009). "Cancers often overexpress growth factors such as EGF to facilitate cell replication and migration." (PMID 19816581, 2009). "Though absent in the microarray, we also investigated the role of EGF in this response because release of this growth factor by TAMs has previously been linked to cancer cell migration in vitro and in vivo." (PMID 19696929, 2009). "Cancers often overexpress EGF and other growth factors to promote cell replication and migration." (PMID 19816581, 2009).
cancer (continued). "Epidermal growth factor stimulates proliferation of various normal and cancer cells." (PMID 19456848, 2009). "The EGF-CFC factor Oep/Cripto1/Frl1 has been implicated in embryogenesis and several human cancers." (PMID 18197245, 2008). "Given the important roles of Src and lipid rafts in mediating EGF/EGFR-regulated cancer development, our results should shed new lights on how cells coordinate molecular activities in space and time to orchestrate pathophysiological responses upon external stimulation." (PMID 18711637, 2008). "This study was to further investigate whether the EGF-targeted phagemid particles carrying siRNA would be a promising tool for anti-cancer siRNA delivery." (PMID 18801171, 2008). "When A431 (a human epithelial carcinoma cell line) cells are stimulated with epidermal growth factor (EGF) myosin VI is recruited into the dynamic ruffling membrane at the leading edge and there is a four-fold increase in the level of myosin VI phosphorylation." (PMID 18068125, 2008). "The CSF1 produced by cancer cells promotes the expression of EGF by macrophages." (PMID 17242701, 2007). "Decreased EGF was found in 72% (18 out of 25) of the patients with a 97.8% specificity (1 out of 45 donors was detected as positive for cancer), when the mean value of the healthy group minus two standard deviations (425.6 pg ml−1) was used as the cutoff point." (PMID 17453000, 2007). "In addition, EGF promotes the expression of CSF-1 by cancer cells, thereby generating a positive feedback loop." (PMID 17242701, 2007). "In addition, cells take up both their own EGF and that secreted by adjoining cells in our model, because cancer cells act in both autocrine and paracrine manner in consuming EGF." (PMID 18154660, 2007). "In vivo, the source of EGF that drives a cancer cell to become invasive may be adjacent cancer cells, adjacent mesenchymal cells, or the cancer cell itself." (PMID 15801978, 2005). "The third group in our study, RCCs with totally negative EGFR staining, may include a group of cancers in which mechanisms other than EGF are responsible for cancer growth and progression." (PMID 14520458, 2003). "Moreover, STAT3 phosphorylation by EGF or IL-6 was diminished in multiple CARP-1 null cancer cells." (PMID 42121855, 2026). "While the effects of EGF on RPE glucose metabolism are unlikely to be as severe as in EGFR-mutated cancer cells, upregulated EGF in the RPE/choroid during aging and AMD may work to increase glycolysis as seen in other non-cancerous cells." (PMID 39433211, 2025). "However, to date, anti-cancer activities of EGF-NPs have only been investigated using gold NPs as EGF carriers, as it is easy to control their diameter, shape, and surface functionalities for the fundamental analysis of their impacts on cellular cytotoxicity and intracellular signaling." (PMID 41140511, 2025). "Thus, EGF has pleiotropic effects on mitochondrial metabolism, even among cancer or non-cancer cells, and its effects on RPE respiration remain unknown." (PMID 39433211, 2025). "EGF may also influence amino acid uptake in non-cancer cells." (PMID 39433211, 2025). "Therefore, we chose its natural ligand, EGF, as a cancer‐targeting moiety." (PMID 40104837, 2025). "Notably, alternative endeavors like MGL S3, a genetically engineered protein formed by combining MGL with an epidermal growth factor (EGF)-like peptide, bind directly to cancer cells, inhibiting their proliferation and enhancing their sensitivity to EGFR inhibitors." (PMID 40430461, 2025). "Receptor tyrosine kinases (RTKs) that respond to the Epidermal Growth Factor (EGF) family of ligands play important roles in development and physiology across metazoa, and dysregulation of EGF receptor (EGFR/ErbB) signaling is associated with several human cancers." (PMID 38545437, 2024).
cancer (continued). "A randomised controlled phase III trial of 80 cancer patients treated with EGFR inhibitors showed that the application of EGF ointment twice daily significantly improved skin toxicities (77.8% response rate using 20 ppm EGF concentration) and patient quality of life." (PMID 39061166, 2024). "Notably, dysregulated EGF/EGFR signal activation is commonly found in cancers." (PMID 37132043, 2023). "Since the use of Nbs for EGF neutralization may be an effective therapeutic strategy in several types of cancer, in this study, we decided to generate anti-EGF nanobodies from our recently constructed synthetic nanobody library, based on the phage-display platform." (PMID 37241784, 2023). "Stimulation by growth factors, such as EGF and TGF plays a key role in the activation of molecular signalling pathways associated with proliferation and cell growth, whereby altered signalling may lead to the development of cancer." (PMID 38027211, 2023). "Moreover, serine and 1-carbon metabolism link mTOR signals to DNA methylation, resulting in oncogene mutations that provide continuous activation of growth factor [insulin-like growth factor (IGF)-1, epidermal growth factor (EGF), and EGF receptor] signals for cancer cells." (PMID 37187454, 2023). "Therefore, along with the EGFR, the EGF is also considered a potential target for cancer therapy." (PMID 37241784, 2023). "Our data shed light on CHD6 upstream regulatory circuit and reveal how EGF/Wnt oncogenic signal promotes CHD6’s downstream activity toward TMEM65 pathway to cause deregulation of mitochondrial dynamics and subsequently promote cancer metastasis and tumorigenesis." (PMID 36473865, 2022). "However, upon EGF stimulation, we observed 10 examples of spliced variants downregulated upon AKT1 silencing, among them many were reported with an alteration related to breast/human cancers." (PMID 35892586, 2022). "Furthermore, TA-MSCs could secrete epidermal growth factor (EGF) which activated the downstream PI3K/AKT signaling to modulate cancer cells proliferative activity." (PMID 36324128, 2022). "It was thought that the EGF content in EBN could be too low to induce cancer growth." (PMID 34658881, 2021). "However, cancer cells often become tolerant to EGF/EGFR signaling-targeted therapies." (PMID 32901097, 2021). "Therefore, KCC3, KCC4, EGF, and IGF-1 may be a panel of promising diagnostic biomarkers to predict cancer patient outcomes." (PMID 35008759, 2021). "In addition, sorafenib has been connected with key signalling pathways in cancer such as EGFR/EGF." (PMID 34655447, 2021). "Inflammatory macrophages play an important role in cancer initiation by creating a mutagenic micro-environment through producing proinflammatory mediators, such as IL-6, TNFα, and interferon-gamma (IFNγ); as well as growth factors, including epidermal growth factor (EGF) and metabolites." (PMID 34207286, 2021). "Hence, PDT and EGF-SubA can more effectively kill cancer cells when used in combination." (PMID 33743739, 2021). "Indeed, the inhibition of either EGF or CSF1 results in strong cancer cell migration diminution." (PMID 33783686, 2021). "CSCs could be enriched by culturing primary or developed cancer cell lines in medium with serum reduction and the presence of growth factors such as EGF and FGF2, in which cancer cells form spheres and become more capable of tumorigeneicity and resistant to chemotherapy." (PMID 31928533, 2020). "Indeed, cancer cells educate monocytes into M2-like macrophages by releasing C-C motif chemokine ligand 2 which in turn secrete EGF, hence increasing cancer cell motility by mean of invadopodia formation, facilitating tumor local invasion and distant metastasis." (PMID 33178698, 2020). "Therefore, determination of the quantity of EGF has significant benefits for cancer diagnostics." (PMID 32764513, 2020). "Therefore, we supposed that EGF/EGFR signal may be critical in regulating PD-L1 expression in many cancers." (PMID 33324209, 2020).
cancer (continued). "Recent studies have indicated that ARL4C could be induced by EGF and promotes the motility of cancer cells by remodeling actin cytoskeleton through Arf6 activation, which might be involved in the migration, invasion, and proliferation of cancer cells." (PMID 33194732, 2020). "However, in cancer cells, cytokine and growth factor receptors become constitutively activated, most commonly by the autocrine or paracrine expression of their respective ligands such as interleukin 6 (IL-6) and epidermal growth factor (EGF)." (PMID 31816985, 2019). "Interestingly, EGF is known to promote cancer progression through EGR1 upregulation." (PMID 30845713, 2019). "Moreover, the ability of EGF to enhance cell migration in serum-free media was observed only in DUOX1-deficient cells, consistent with previous findings linking DUOX1 silencing to increased epithelial-to-mesenchymal transition and cancer cell invasiveness." (PMID 30890751, 2019). "We show that GroPIns4P is required for EGF-induced fibroblast migration and that it is part of a cPLA2/GroPIns4P/Shp1/Src cascade that might have broad implications for studies of immune-inflammatory response and cancer." (PMID 30823936, 2019). "Accordingly, EGF-induced ERK activation has previously been found to be enhanced and/or sustained in T-REx293T cells expressing NS-associated RIT1 mutants, and ectopic expression of NS- and cancer-related RIT1 mutants in PC6 cells induced phosphorylation of both MEK and ERK." (PMID 29734338, 2018). "In addition to VEGF, cancer cells secrete other angiogenic factors, such as basic fibroblast growth factor (bFGF), angiopoietins (Ang), hepatocyte growth factor, epidermal growth factor (EGF), platelet-derived growth factor (PDGF), and placental-derived growth factor." (PMID 29695087, 2018). "Meanwhile, whether Fas has a role in EGF-dependent EGFR activation in cancer remained unknown." (PMID 30127519, 2018). "Although EGF–EGFR signaling is only one of several pathways involved in cancer cell proliferation and motility, the respective effects of EGF and Rab25 on integrin localization revealed in the present study may partially explain the diverse effects of EGFR-targeting drugs." (PMID 29515334, 2018). "Technically, to obtain this reservoir for CSCs, cancer cells are cultured in serum-free medium and supplemented with various factors, including basic fibroblast growth factor (bFGF) and epidermal growth factor (EGF), hydrocortisone, insulin, progesterone, and heparin." (PMID 29416698, 2018). "EMT can be induced by growth factors such as transforming growth factor beta (TGF-β), epidermal growth factor (EGF), hepatocyte growth factor (HGF), insulin-like growth factors 1 and 2, activating RAS, Notch, and Wnt signalings which have been associated with poor prognosis and cancer progression." (PMID 29189742, 2017). "Considering this, we hypothesized that ATXN1 is involved in EGF-mediated cancer growth." (PMID 29212253, 2017). "Most of the regulated Cys sites have never been associated with EGF signaling before and this could open up for various new ideas to manipulate this pathway, which is very central in diseases such as cancer." (PMID 27281782, 2016). "A hypothesis-generating whole transcriptome analysis shows that HBL tumors removed at transplantation are enriched most for cancer signaling pathways which depend predominantly on epidermal growth factor (EGF) signaling, and to a lesser extent, on aberrant Wnt-β-catenin signaling." (PMID 27910913, 2016). "Due to the high specificity of QD-labeled EGF interaction with the cells and demonstrated here preferable accumulation of the label in the cells overexpressing EGF receptors, it can be used for target delivery of multifunctional therapeutic drugs in case of cancers with high level of EGF receptors." (PMID 26716513, 2016).
cancer (continued). "We use the Michaelis-Menten law to express the enhanced proliferation of fibroblasts by Tβ (i.e., by c1C) because TGF-β activation of fibroblast and EGF enhancement of cancer cells may be limited due to the limited rate of receptors recycling associated with this process." (PMID 27078836, 2016). "Our results showing that EGF induced BMP-4 further suggest the existence of a new functional relationship between both proteins that may be critical in the control of the invasive behavior of cancer cells." (PMID 25897433, 2015). "Since EGF and bFGF play critical roles in malignant progression and stemness in many cancers and we have found that C1GALT1 can modulate sphere forming ability induced by EGF and bFGF, we therefore analyzed whether these two signaling pathways are involved in the C1GALT1-mediated phenotypic changes." (PMID 24758762, 2014). "Furthermore, our findings may lend support for the pursuit of anti-EGF therapy, not only for preventing cancer or disrupting carcinogenesis, but for decreasing the negative impact on cognitive functioning." (PMID 24495355, 2014). "Recent data showed that EGF could stimulate the migration of cancer cells." (PMID 23613900, 2013). "Indeed, AR mediates EGF proliferative activity in various cancer cells." (PMID 24130806, 2013). "In addition, the expression of COX-2 can be triggered by EGF or histamine in cancer cells." (PMID 23774942, 2013). "Additionally, inhibition of EGF signaling leads to inhibition of cancer initiation and progression." (PMID 24040120, 2013). "In addition, overexpressed FER could phosphorylate EGF receptor and activate the EGF-mediated NF-κB signaling pathway, which is crucial for cancer cell survival and proliferation." (PMID 23420638, 2013). "Since core-fucosylation regulates cell surface glycoproteins such as epidermal growth factor and transforming growth factor beta receptors directly, and loss of fucosylation brings dramatic changes in TRAIL signaling fucosylation is a promising target for cancer diagnosis and therapeutics." (PMID 24970126, 2012). "Thus, the requirement for MUC1 in vitro and in vivo could represent a general mechanism to drive the metastatic phenotype for carcinoma cells which are dependent upon EGF/EGFR/Src signaling." (PMID 22586492, 2012). "By the same mechanism cancer cells may acquire resistance to EGF pathway inhibitors." (PMID 21464922, 2011). "As both EGF and survivin are essential for β-cell proliferation, and as survivin expression is regulated by EGF in cancer cells, we hypothesized that EGF also regulates survivin expression in β-cells and thereby is one of the mechanisms involved in promoting β-cell growth." (PMID 20807437, 2010). "Consequently, these signals might be potential targets for further biological investigation on how different doses and treatment conditions with TNF, EGF or insulin lead to different death/survival decisions in cancer cells." (PMID 17559646, 2007). "Consequently, the original aim was to investigate how the apoptosis signaling network was activated in response to different levels of TNF, EGF and insulin and how such differential activation contributes to antagonistic cellular decisions, such as cell death versus survival in cancer cells." (PMID 17559646, 2007). "Upon activation by ligands such as EGF, EGFR phosphorylates downstream effectors like STAT3, a transcription factor critical for cancer cell proliferation and survival." (PMID 41511366, 2026). "We then visualized and quantified the oligomerization of the cancer therapeutic target EGFR in the resting state and upon binding to its ligand, EGF, in whole intact cells." (PMID 40328783, 2025). "Mechanistically, agrin mechanoactivates EGFR through epidermal growth factor (EGF)‐dependent and independent modes, thereby sensitizing its activity toward localized cancer cell‐ECM adherence and bulk rigidity by fostering interactions with integrin β1." (PMID 40165020, 2025).